IL6 (interleukin 6)
Diseases named in the same sentence as IL6 in open-access papers (continued):
Sharing a sentence is not in itself a finding about the gene and the disease.
tumor (continued). "Cytokines including IL-6, VEGF, IGF-1, TNFα, and HGF produced from bone marrow stromal cells (BMSCs) and tumor cells directly and/or indirectly influence MM cells in autocrine and paracrine manners." (PMID 24151609, 2013). "Expression of chemokine for monocytes (CSF-1 and CCL-2) were low in tumor cells from EGCG-treated mice, and cytokines of TAM was skewed from M2- into M1-like phenotype by EGCG as evidenced by decreased IL-6 and TGF-β and increased TNF-α." (PMID 24044575, 2013). "Further, we demonstrated that the GMF-mediated induction of Th17 occurred via IL-6 and TGF-β, which are not only increased by C-GMF, but are also important cytokines in both Th17 development and in tumor development." (PMID 23365642, 2013). "Of those molecules a number of have been associated with cell migration/invasion, tissue remodeling and inflammatory response, processes that are likely to influence tumor cell invasion, including MCP-3 (CCL7), osteopontin, TGFB-1, IL-6 and IL-8." (PMID 23349962, 2013). "IL6, a direct regulator of breast CSC self-renewal activates STAT3 and NF-κB which secretes additional IL6 and IL8, generating a positive feedback loop between inflammatory cell and tumor cells." (PMID 23799116, 2013). "IL-6/STAT3 signaling was reported to stimulating tumor invasion, EMT changes, and promote the surviving tumor cells after therapy to acquire treatment resistance via microenvironment- mediated resistance." (PMID 23806095, 2013). "In conclusion, IL-6-induced activation of STAT3 is observed in neoplastic gastric tissue, which positively correlated with tumor progression." (PMID 24116074, 2013). "For example, ZR-shEI24 cells exhibited upregulation of IL6 and IL8, NF-κB target genes that are involved in inflammation-induced tumor metastasis." (PMID 24280371, 2013). "Preclinical evidence has shown that IL6 enhances tumor cell survival and increases resistance to chemotherapy via JAK/STAT signaling in tumor cells and IL6 receptor alpha trans-signaling on tumor endothelial cells." (PMID 23889749, 2013). "This stimulatory activity of EVs to induce secretion of TGF-β1, MMP-9, IL-6 and EMMPRIN, suggests a role of the EVs in driving tumor progression by stimulating factors important for immune evasion, invasion and inflammation." (PMID 23936495, 2013). "Although inflammation has been shown to be a hallmark of cancer, and several pro-inflammatory cytokines play a role in tumor progression, IFN-γ and IL-6 have been described as key elements in host anti-tumor immune response." (PMID 23691222, 2013). "Matrix metalloproteinase-2 (MMP-2) and IL-6 participate in endothelial cell injury and the extravasation of tumor cells, and IL-1β, IL-6, and TGF-β are involved in tumor progression." (PMID 23710200, 2013). "In this study the levels of TNF-α, IL-6, COX-2 and VEGF in tumor microenvironment were reduced by virtue of addition of fish oil." (PMID 23349693, 2013). "MSCs can enhance CSCs proliferation by secreting cytokines, IL-6 and CXCL7, thereby facilitating the tumor growth." (PMID 23336752, 2013). "It has been reported that IL-6 is a major activator of STAT3 signaling, and the activation of STAT3 signaling plays a role in the induction of aggressive tumor behavior and EMT changes in cancer." (PMID 23637926, 2013). "We showed that the hyper-IL-6 cytokine was successfully produced by GLV-1h90 and was functional both in cell culture as well as in tumor-bearing animals, in which the cytokine-producing vaccinia virus strain was well tolerated." (PMID 22236378, 2012). "For example, tumour-necrosis factor-α, interleukin-6 and TGF-β seem to be crucial for tumour initiation, because they stimulate the inhibition of the NF-κB pathway in epithelial cells." (PMID 23095257, 2012). "Of special interest was the presence of hyper-IL-6 in blood serum samples of GLV-1h90-injected mice, which is essential for its ability to induce signal transduction pathways outside the tumor." (PMID 22236378, 2012).
tumor (continued). "Only IL6 and IL8 demonstrated a significant elevation in plasma concentration between borderline tumours and early stage (Stage I-II)." (PMID 22410202, 2012). "We also saw clear examples of the complexity of tumour biology, where TNF-α/IL-6 pathways were activated by DMXAA in both A375 cells and stromal cells." (PMID 22415295, 2012). "We then detected cytokines IL-1β, IL-6, IL-17A, IL-21, IL-23 or TGF-β by ELISA in sera and supernatants from both normal and tumor tissues cultured ex vivo." (PMID 22994684, 2012). "Both SE and EE tumor-bearing mice presented a significant increase in systemic inflammatory markers, including, IL-6, TNF-α, MCP-1, PAI-1 and resistin very likely due to the presence of the tumor." (PMID 23272114, 2012). "Tumor infiltrating immune cells such as CD4+, CD8+ and FOXP3+ T-cells and macrophages secrete soluble effector molecules such as interferons, IL-6 and TNF, and some of these can directly influence innate immune gene expression in keratinocytes." (PMID 22808251, 2012). "We used a multistage model of SCC to examine the involvement of elastase (ELA), myeloperoxidase (MPO), nitric oxide (NO), cytokines (IL-6, IL-10, IL-13, IL-17, TGF-β and TNF-α), and neutrophils and macrophages in tumour development." (PMID 23176085, 2012). "The expressions of numerous cytokines that are growth factors for tumor cells such as interleukin 1β (IL-1β); tumor necrosis factor (TNF); epidermal growth factor (EGF) and IL-6 are also regulated by NF-κB." (PMID 22873280, 2012). "Accordingly, in the AOM + DSS mouse model, Becker and colleagues demonstrate that IL-6 is highly produced by CD4+ T cells and promotes tumor cell proliferation via STAT3 activation." (PMID 23109839, 2012). "IL-6 in particular is an autocrine growth factor for RCC and seems to be tumor protecting against cytotoxic tumor-infiltrating lymphocytes." (PMID 22139406, 2012). "More specifically, IL-6 and IL-10 collectively promote growth of KSHV-infected tumor cells, angiogenesis and suppression of T-cell activation." (PMID 22505930, 2012). "Cytokines such as interleukin (IL)-6, IL-17A, IL-21 and tumor necrosis factor (TNF)-α contribute to the formation of a tumor-supportive microenvironment, while interferon (IFN)-γ is supposed to exert tumor-suppressive functions." (PMID 23109839, 2012). "In this study, we found that high expression of cytosolic IL6 in OSCC tumors is correlated with female gender, a high rate of lymph node metastasis, and poor tumor differentiation." (PMID 23185547, 2012). "After treatment with TβRI kinase inhibitor (SD-208), decreased production of IL-6 and VEGF and also attenuated tumor cell growth was observed." (PMID 22943793, 2012). "iNOS can be induced in myeloid cells by different tumor-secreted factors such as VEGF, GM-CSF, and IL-6." (PMID 22481970, 2012). "Increased production of TGF-β is followed by increased interleukin-6 (IL-6) and vascular endothelial growth factor (VEGF) secretion by BMSC, related to tumor cell proliferation." (PMID 22943793, 2012). "We also proposed that the mammosphere culture is able to enrich CSCs from tumor samples as a result of cytokines in the mammosphere media inducing EMT in cancer cells, in a similar manner to IL-6." (PMID 22134360, 2012). "Tumor ER stress c.m. -imprinted (TERS-imprinted) BMDC also upregulated the transcription of the pro-inflammatory, pro-tumorigenic cytokines Il-6, Il-23p19, and, in two of three cell lines, Tnf-α." (PMID 23272178, 2012). "Although not induced themselves by DMXAA at the RNA level, NF-κB, TNF-α, IL-6 and IFN-β have several downstream targets that are differentially expressed between control and DMXAA-treated tumours." (PMID 22415295, 2012). "Therefore, it is possible that IL-6 might participates primarily in tumor progression." (PMID 22912790, 2012).
tumor (continued). "Tumor cells, stromal cells like fibroblasts, and tumor-infiltrating immune cells and/or their secreted products, like VEGF, M-CSF, IL-6, IL-10, and TGF-β are also responsible for systemic and local DC defects." (PMID 23217146, 2012). "This was accompanied by decreased levels of IL-6 and TGF-β, increased numbers of IFN-γ and TNF-α producing CD4+ T cells as well as a significant reduction of tumor growth." (PMID 22855687, 2012). "In PGCG, the TNF-α, IL-6 and IL-1β interrelations may control the cellular activities of the different cell populations (multinuclear cells, monocytes/macrophages, spindle fibroblasts/osteoblasts) contributing possibly mainly in the mechanisms of tumor growth, and occasionally of osteolysis." (PMID 22157665, 2012). "One would predict that this is the case, because prostaglandins, which are products of COX-2 activity, can upregulate IL-8, IL-6, VEGF, and HIF1α in tumor epithelial cells." (PMID 23216814, 2012). "The tumor microenvironment has immune suppressive mediators such as PGE2, TGF-β, IL-10, VEGF, GM-CSF, IL-6, S100A8/A9 and SCF that recruit and/or activate MDSC." (PMID 22815789, 2012). "In the case of chronic inflammation, the cytokine profile at the tumor microenvironment is dramatically different and is characterized by an increase in immunosuppressive cytokines, such as TNF-α and IL-6." (PMID 22530148, 2012). "Previous reports demonstrated a high expression of IL6 in OSCC tumor cells or premalignant lesions, including dysplasias, when compared with non-tumor oral epithelium." (PMID 23185547, 2012). "Eight of these immune response genes (SPP1, PDPN, IL1RN, IL6, CCL8, MDK, IRF7, and HRH4) were expressed between 1.25–1.59 fold higher in the microglia/macrophage enriched population compared to bulk tumor." (PMID 22937035, 2012). "The components of the microenvironment including the bone marrow stromal cells (BMSCs) and cytokines such as IL6, IGF and VEGF are well known to be important mediators of tumor growth and drug resistance in MM." (PMID 23185517, 2012). "Expressions of interleukin-6 (IL-6), IL-8, interferon (IFN)-gamma, and tumor necrosis factor (TNF)-alpha mRNAs were also detected in tumor tissue, while IL-1-alpha, IL-1-beta, IL-2, IL-4, and COX-2 mRNAs were not." (PMID 22844297, 2012). "CDF treatment decreased the relative mRNA levels of HIF-1α, VEGF, IL-6, CD44, and EpCAM in MiaPaCa-2 tumor sphere cells under hypoxic conditions." (PMID 23272057, 2012). "Relative to untreated MDA-MB-231 tumor xenografts, the xenografts from mice treated with UTI, TAX, and UTI+TAX showed decreased expression of IL-6, IL-8, and TNF-α proteins." (PMID 21345194, 2011). "Second, in co-culture experiemtns with monocytes and tumor cells, monocytes enhance HCC cell proliferation, which was dependent on IL-6/STAT3 signaling pathway." (PMID 22136659, 2011). "While CTLA-4 blockade did increase IFN-γ production from CD8 T-cells in the vaccine and tumor draining lymph nodes, α4-1BB evoked much stronger increases in IFN-γ, TNF-α, and IL-6 production." (PMID 21559358, 2011). "We have observed that differential TG2 expressions of cancer cells were dictated into their IL-6 production, and TG2 and downstream IL-6 production from cancer cells wase correlated with their capacity for tumor-sphere formation in vitro." (PMID 21967801, 2011). "The regulation was further controlled by breast-tumour cell-derived IL-6 stimulating both the secretion of CXCR7 and the chemotaxis of MSCs to the tumour cells." (PMID 21902837, 2011). "Tax tumor cells express IL-6, M-CSF, IL-1, TNF-α, and Tax expression enhances IL-6 and TNF-α expression in vitro and in vivo." (PMID 21994759, 2011). "Anti-CRD4 MR scFv #G11 preserved CD206low macrophage phenotype during co-culture with tumor cells, as shown by the up-regulation of IL-12 (condition 4), TNF-α (conditions 4, 6), and IL-6 (conditions 4, 6)." (PMID 22163010, 2011).
tumor (continued). "Next, we determined serum levels of the proinflammatory and tumor-promoting cytokines, tumor necrosis factor alpha (TNF-α) and interleukin (IL)-6." (PMID 21725989, 2011). "When pro-tumor growth mediators such as IL-6, IL-10, MMP-9, and VEGF are the primary secreted factors from TAMs, then tumor angiogenesis, enhanced cell motility, and increased tumor cell invasion are facilitated." (PMID 21385454, 2011). "Neutralizing antibodies to cytokines GM-CSF, IL-1β, IL-6, VEGF, or TNFα were tested in PBMC-tumor cell line co-cultures to determine which factor(s) was most important for induction." (PMID 21658270, 2011). "By day 7, IFNγ, CSF2, CXCL10, GZMB, PTGS2, TNFα, CD80, CCL22, IL12a, IL13, IL1b, IL6, NOS2, and CTLA4 were significantly upregulated in the tumor-bearing mice bladders and AGTR2 and GATA3 were downregulated." (PMID 22013484, 2011). "One study of oesophagogastric cancers showed cytokine protein concentrations of IL-1β, IL-6 and TNF-α are significantly elevated in tumour tissue." (PMID 21760776, 2011). "Different inflammatory mediators, for example, cyclooxygenase-2 (COX-2), IL-1, IL-6, TGFβ and CXCL8, and their receptors are present in the tumor milieu." (PMID 22190968, 2011). "Plasma analyte profiling of both moderately and severely cachectic mice revealed that circulating levels of IL-6 and three other gp130 ligands, IL-11, leukemia inhibitory factor (LIF) and Oncostatin M were significantly increased in tumor-bearing mice." (PMID 21799891, 2011). "Interestingly, IL-6 over-expression did not induce muscle wasting in non-tumor bearing mice, indicating that IL-6 may cause muscle wasting indirectly by increasing tumor burden." (PMID 21832306, 2011). "In vitro tumor-sphere formation was dependent on TG2 and downstream IL-6 production from cancer cells." (PMID 21967801, 2011). "Primary tumor growth in the mammary fat pads and distant hematogenous metastasis into the lung was also dependent on TG2 and downstream IL-6 expression levels." (PMID 21967801, 2011). "An IL-6 neutralizing mAb reduced STAT3 activation and also completely reversed IL-17-stimulated tumor invasion in vitro, while exogenous IL-6 completely recovered IL-17-induced invasion of siRNA-AKT-SMMC7721 and siRNA-AKT-Huh7 cells." (PMID 22171994, 2011). "Onconase treatment consistently resulted in up-regulation of IL-24, previously shown to have tumor suppressive activity, as well as ATF3 and IL-6." (PMID 20137089, 2010). "There is evidence that major inflammatory cytokines (such as IL-1β, IL-6, IL-23 and TNF-α promote tumor development by acting directly or indirectly on neoplastic cells." (PMID 20525350, 2010). "Many proteins that are crucial for tumor cell proliferation and survival have been found to be regulated by STAT3; these include Bcl-2, Bcl-XL, cyclin D1/D2 and IL-6, which are considered to contribute to the anoikis resistance-inducing property of STAT3." (PMID 20507639, 2010). "There is evidence that some inflammatory cytokines (such as IL-1β, IL-6, IL-23 and TNF-α promote tumor development by acting directly or indirectly on neoplastic cells." (PMID 20525350, 2010). "The fourth and final characteristic that defines a TAF is secretion of tumor-supportive growth factors, including HGF, EGF and IL6." (PMID 19352430, 2009). "RFA has a strong catabolic effect on tumor cells that are producing nerve-stimulating cytokines such as tumor necrosis factor-alpha (TNF-α), interleukins (IL-1 and IL-6), resulting in inhibition of osteoclast activity." (PMID 19917114, 2009). "Our results stress the importance to evaluate the endogenous levels of IL-6 and IL-6Rα in each NPC individually, if cultured NPC cells of the given tumor are to be considered for making tumor vaccines." (PMID 19497133, 2009). "We further demonstrate that the microenvironment provided by the tumor stimulated MSC directly to enhance the growth of Skov-3, which is significantly enhanced by growth factors interleukin-6 (IL-6) and EGF." (PMID 19352430, 2009).
tumor (continued). "In this study, the serum levels of both IL-6 and CRP evidenced statistically significant differences in tumor size, tumor invasion depth, and LN metastasis." (PMID 19457231, 2009). "Moreover, it is tempting to speculate that to establish a micrometastasis in the bone marrow, only tumor cells secreting high levels of IL-6 within the primary tumor cell population may manage to survive in the new microenvironment, i.e., bone marrow, which is so different from the primary site." (PMID 19497133, 2009). "The 52 analysed tumour specimens revealed a heterogeneous staining pattern for IL-6 and TGF-β1 with variably intense cytoplasmatic and/or nuclear staining of the tumour cells." (PMID 18682839, 2008). "In most patients IL-6 and TGF-β1 plasma levels were already elevated before RT and correlated significantly with the IL-6 and TGF-β1 production in corresponding tumour biopsies." (PMID 18682839, 2008). "In contrast, IL-6 and TGF-β1 plasma levels measured in patients with advanced NSCLC depend to a great extent on the cytokine production in their tumours." (PMID 18682839, 2008). "IL-6 protein was rapidly and strongly enhanced in the PDT treated tumors at 24 h suggesting a strong immune response which potentiates anti-tumor immunity." (PMID 18549507, 2008). "Moreover, IL-6 promotes tumour growth and may induce chemoresistance." (PMID 18728665, 2008). "Interleukin-6 (IL-6) mRNA and protein are upregulated in certain tumour cells after PDT in vitro and IL-6 is generally the most markedly enhanced cytokine in tumour tissues after PDT in vivo." (PMID 17987036, 2007). "Most of the cytokines that were preferentially present in ER-negative tumours (IL-1β, IL-6, IL-8, IL-10, IL-12, MCP-1 and MIP-1β) were also more abundant in high-grade tumours." (PMID 17261184, 2007). "Recently, Roepman and coworkers reported that cluster B genes IL6, IL8, YAP1, and BIRC2 are upregulated in metastatic HNSCC tumor specimens." (PMID 17498291, 2007). "Similar to the experiments with sgp130, tumour regrowth after PDT, when it occurred, commenced at the same time in Hyper-IL-6 and control groups, and proceeded at the same rate." (PMID 17987036, 2007). "On the other hand, IL-2, IL-6, IL-8, IL-10, IFN-γ, MCP-1, MIP-1β, TNF-α and, to a lesser extent, IL-1β and IL-13 were significantly overexpressed in ER-negative tumours compared with ER-positive ones, with the greatest differences observed for IL-8 and MCP-1." (PMID 17261184, 2007). "In this context, it is noteworthy that even the concentrations of IL-6 and TNF-α were found to be elevated in ARC in tumor-bearing rats." (PMID 18078524, 2007). "The significant reduction in plasma IL-6 level and EBV DNA load suggest a state of inflammation that was most probably triggered by EBV infection of tumour cells." (PMID 16995954, 2006). "Tissue cytokine (IL-1β, IL-6, IL-8, and TNF-α) mRNA and protein levels were found at similar concentrations within tumour tissues with a chronic inflammatory cell infiltrate and tumour samples with lymphoid aggregates alone." (PMID 17088911, 2006). "The cytokines most often detected in serum and ascites of patients with EOC include TNFα, IL-10, IL-6, CSF1 (MCSF), IL-1, and TGFβ isotypes, all of which can be produced by activated MA or by the tumor cells." (PMID 16824216, 2006). "Interleukin-6 is the main inducer of the APPR in human hepatocytes and both IL-1β and TNF-α are capable of inducing IL-6 production from both tumour and host cells." (PMID 17088911, 2006). "In contrast, mRNA for IL-1β, IL-6, IL-8, and TNF-α were detected in tumour tissue at significantly elevated concentrations: IL-1β P<0.001; IL-6 P<0.001; IL-8 P<0.001; TNF-α P=0.006." (PMID 17088911, 2006). "The multivariate analysis included tumor stage (T3-4 vs. T1-2), nodal stage, perfusion (≥ median), VEGF serum level (≥ median) and IL-6 serum level (≥ median)." (PMID 15847702, 2005).